RBFOX1 (RNA binding fox-1 homolog 1)
Diseases named in the same sentence as RBFOX1 in open-access papers (continued):
Sharing a sentence is not in itself a finding about the gene and the disease.
cancer (28 papers, 2010 to 2024). A tumor composed of atypical neoplastic, often pleomorphic cells that invade other tissues. "As expected, cancer-destabilized mRNAs that were associated with RBFOX1 were also downregulated upon RBFOX1 knockdown." (PMID 35987939, 2022). "In this study, the expression of the RBFOX1 gene (or A2BP1), which had decreased expression in the high-grade group compared with the low-grade group, differed in 13 cancer types." (PMID 38167455, 2024). "We noticed a subset of mRNAs that are consistently destabilized across the same cancers in which either RBFOX1 or RBFOX3 is downregulated." (PMID 35987939, 2022). "We identified a core set of eight transcripts that have RBFOX binding site in their 3ʹ UTRs, are concurrently destabilized across cancers, are inhibited when RBFOX1 is knocked down, and are upregulated when RBFOX1 expression is rescued." (PMID 35987939, 2022). "Taken together, these observations suggest that RBFOX1/3 are the most likely candidates driving dysregulation of the RBFOX regulon in cancer." (PMID 35987939, 2022). "We performed a proof‐of‐concept demonstration with the degradation of two RBPs—a stem cell factor LIN28 and a splicing factor RBFOX1—and showed their use in cancer cell lines." (PMID 33108679, 2021). "RBFOX1 promotes mRNA stability and it is down-regulated across multiple cancers types." (PMID 38566223, 2024). "Furthermore, the majority of pan-cancer destabilized mRNAs that are bound by RBFOX1 are upregulated in A172 cells after RBFOX1 overexpression." (PMID 35987939, 2022). "Furthermore, our results are confirmed by the literatures, with 6 out of top 10 features associated with specific cancers including NKIRAS1, CDKN2B, YTHDC2, MECOM, RBFOX1, and RAB6B." (PMID 33329723, 2020). "Integration events occurring in single samples were observed in the following cancer-driver genes: TERT, KMT2B (MLL4), RIMS1, FN1, RBFOX1, CNTNAP2 and THRB7,11,12,14,27,28." (PMID 37400627, 2023). "Among the RBPs we analysed, two RBPs, namely RBFOX1 and RBFOX3, stand out as being consistently deregulated across several cancer types." (PMID 35987939, 2022). "Several genomic regions containing fragile sites, such as the FHIT gene locus at 3p14.2, RBFOX1 at 16p13.3 and MACROD2 at 20p12.1 that were targeted for deletion in MSS cancers, were also relatively commonly deleted in BRAFmut/MSI cancers." (PMID 24651849, 2014). "Alternative splicing is a key feature of cancer including CRC and the identification of RBFOX1 targets in CRC will help to determine if RBFOX1 deletion is a critical feature of dysfunctional splicing in CRC." (PMID 23286373, 2013). "The BRAFmut/MSI cancers had substantially fewer MCRs than the MSS cohorts, however they did have a comparatively high proportion of cancers (≥20%) with focal deletions at 3p14.2 (FHIT), 16p13.3 (RBFOX1) and 20p12.1 (MACROD2)." (PMID 24651849, 2014). "Moreover, we compared cancer cell expression with mRNA levels in healthy neural progenitor cells and mature neurons for essential neuronal RBPs such as FMRP, RNA-binding protein fox-1 (Rbfox1), Staufen2 (Stau2), and Pum2." (PMID 34445704, 2021). "In contrast, Rbfox1, FMRP, and Stau2 were either not enriched in cancer cells or showed reduced expression compared to Pum2." (PMID 34445704, 2021).
psychiatric disorder (19 papers, 2015 to 2025). A disorder characterized by behavioral and/or psychological abnormalities, often accompanied by physical symptoms. "The RNA Binding Fox-1 Homolog 1 (RBFOX1) gene encodes a neuronal splicing factor with a pleiotropic effect on numerous neurological, neurodevelopmental, and psychiatric disorders." (PMID 38399469, 2024). "RBFOX1 is a splicing factor implicated in many neurodevelopmental and psychiatric disorders and several evidences have highlighted this gene as a candidate for aggression." (PMID 29858598, 2019). "The results of this study support the notion that disrupted RBFOX1-iso1 function accounts for the emergence of the clinical symptoms in neurodevelopmental and psychiatric disorders caused by RBFOX1 gene abnormalities." (PMID 27481563, 2016). "While functioning primarily as a splicing regulator, RBFOX1 has also been shown to stabilise target mRNA levels in the cytoplasm, and it controls extensive gene networks implicated in various neurodevelopmental and psychiatric disorders." (PMID 38399469, 2024). "In addition, RBFOX1 was presented as a strong candidate for susceptibility to aggressive behavior and to several psychiatric disorders." (PMID 37686494, 2023). "Rbfox1 is one of the risk genes that are common to PD and various psychiatric disorders." (PMID 36142685, 2022). "These included the MHC region; DRD2, the dopamine D2 receptor involved in mood and emotion; MEF2C, a gene that regulates synaptic function; TCF4, a regulator of prefrontal neuronal excitability and RBFOX1, a gene splicing regulator that has also been implicated in other psychiatric disorders." (PMID 31576797, 2020). "RBFOX1 functions as a master regulator of thousands of genes, exerting a pleiotropic effect on numerous neurodevelopmental and psychiatric disorders." (PMID 38399469, 2024). "This aligns with a previous GWAS meta-analysis across eight psychiatric disorders where RBFOX1 was recognised as the second most pleiotropic locus." (PMID 38399469, 2024). "Given its significant role in neurodevelopment and psychiatric disorders, the study of RBFOX1 has garnered considerable interest in recent years." (PMID 38399469, 2024). "Further intensive analysis of the molecular machinery downstream of RBFOX1-mediated splicing should contribute to a better understanding of the mechanisms of neurodevelopmental and psychiatric disorders where RBFOX1 abnormalities are involved." (PMID 27481563, 2016). "Thus, our data contribute to a better understanding of the involvement of RBFOX1 in psychiatric disorders and point to a pleiotropic contribution of this gene that can be modulated by other environmental and genetic factors." (PMID 38374212, 2024). "Functional abnormalities in Rbfox1-iso2-deficient neurons may induce structural and functional defects of the cerebral cortex and consequently contribute to the clinical symptoms of ASD and other neurodevelopmental and psychiatric disorders with RBFOX1 gene abnormalities." (PMID 26500751, 2015). "Interestingly, RBFOX1 has been reported in several ASD genetic studies, as well as in studies of aggressive behaviour and several psychiatric disorders." (PMID 32545830, 2020).
neurodevelopmental disorder (18 papers, 2014 to 2025). A behavioral and cognitive disorder with onset during the developmental period that involves impaired or aberrant development of intellectual, motor, or social functions. "Abnormal alternative splicing is also associated with neurodevelopmental disorders; for instance, Rbfox1 is a transcription regulator that controls alternative splicing and its mutation is associated with ASD." (PMID 33362469, 2020). "Rbfox1 is a dosage-sensitive gene and in both mice and humans, decreased expression of Rbfox1 has been linked to neurodevelopmental disorders." (PMID 32431595, 2020). "Finally, several point mutations and copy number variations (CNVs) in RBFOX1 have been described in patients with neurodevelopmental disorders, such as ASD and ADHD." (PMID 38374212, 2024). "RBFOX1 regulates alternative splicing events of genes critical for neuronal development and it has been strongly implicated in the etiopathogenesis of a wide spectrum of neurodevelopmental disorders including ASD." (PMID 32081867, 2020). "RBFOX1 is linked to the etiology of neurodevelopmental disorders." (PMID 32431595, 2020). "Abnormalities in the Fox-1 encoding gene, RBFOX1, are associated with neurodevelopmental disorders." (PMID 33329073, 2020). "The abnormal process may underlie the basic pathophysiology of ASD and other neurodevelopmental disorders and may contribute to the emergence of the clinical symptoms of the patients with RBFOX1 gene abnormalities." (PMID 26500751, 2015). "RBFOX1 is a highly pleiotropic gene that contributes to several psychiatric and neurodevelopmental disorders." (PMID 38374212, 2024). "A recent study of RBFOX1 as a candidate gene for aggressive behaviour has highlighted the contribution of RBFOX1 to aggression and to other psychiatric and neurodevelopmental disorders that often manifest aggression." (PMID 36833409, 2023). "Many Rbfox1 target candidates take part in cortical development and neurodevelopmental disorders including ASD." (PMID 27481563, 2016). "Accumulating clinical reports strongly suggest the involvement of RBFOX1 in various neurodevelopmental disorders." (PMID 26500751, 2015). "In humans, heterozygous CNVs in the 5’-noncoding part of the RBFOX1 gene that typically only affect some but not all RBFOX1 transcript isoforms are associated with a range of neurodevelopmental disorders." (PMID 32431595, 2020). "Thus, we here carried out comprehensive analyses of Rbfox1-iso1 to elucidate its role in neurodevelopmental disorders." (PMID 27481563, 2016). "Defects in these critical processes may induce structural and functional defects in cortical neurons, and consequently contribute to the pathophysiology of neurodevelopmental disorders with RBFOX1 abnormalities." (PMID 27481563, 2016). "Impairment of Rbfox1-iso1 function may induce structural and functional defects of the cerebral cortex, and consequently contribute to the clinical symptoms of ASD and other neurodevelopmental disorders with RBFOX1 gene abnormalities." (PMID 27481563, 2016). "The clinical symptoms of ASD and other neurodevelopmental disorders with RBFOX1 gene abnormalities may reflect the observed cellular phenotypes." (PMID 27481563, 2016). "Furthermore, molecular, cellular, and clinical evidence supports a pivotal role of RBFOX1 in human neurodevelopmental disorders." (PMID 25950944, 2015). "Since cell biological relevance of RBFOX1 in the brain development has been enigmatic, we carried out comprehensive in vivo and in vitro analyses to obtain information to understand the etiology of ASD and other neurodevelopmental disorders in which RBFOX1 gene abnormalities are involved." (PMID 26500751, 2015). "Since Rbfox1-iso1 was shown to regulate synaptic structure, this molecule seems to play a pivotal role in the synaptic function, of which dysregulation may contribute to the pathogenesis of neurodevelopmental disorders." (PMID 27481563, 2016).
neurodevelopmental disorder (continued). "Since various neurodevelopmental disorders including ASD are thought to be “synapse” diseases, Rbfox1-iso1 should be involved in axon and dendrite network formation." (PMID 27481563, 2016). "Each of the CNVs described so far in patients with neurodevelopmental disorders affect some, but not all, of the alternative RBFOX1 transcripts." (PMID 32431595, 2020). "The results obtained here indicate that Rbfox1-iso2 may play a crucial role in cerebral cortex development independently of the nuclear isoform Rbfox1-iso1, and functional defects of Rbfox1-iso2 may be related to the etiology of ASD and neurodevelopmental disorders with the gene abnormalities." (PMID 26500751, 2015).
neurological disorders (9 papers, 2013 to 2023). "The study of post-transcriptional regulation by Rbfox1 is an area of interest for understanding the control of cell homeostasis and misregulation in neurological diseases." (PMID 24278214, 2013). "Numerous splicing factors identified here have been reported to have functions in neuronal differentiation, neurological diseases, or synaptic plasticity, such as ELAVL2, ZIC1, A2BP1 (official gene symbol Rbfox1), and FUS." (PMID 24758366, 2014).
cardiovascular disease (3 papers, 2017 to 2021). "In summary, we identified rare, exonic variants in RBFOX1 that have a protective effect on BP traits, which can be important in searching new drugs for cardiovascular disease." (PMID 28346479, 2017). "Hence, Rbfox1 is expressed in multiple tissues that may relate to blood pressure, and the identification of these rare coding variants will facilitate precision medicine in treating cardiovascular disease." (PMID 29181036, 2017).
heart disease (3 papers, 2018 to 2022). "Among the mRBP-coding genes with a high HSS, we found genes coding for well-known heart-disease causing splicing factors, such as RBM20 (HSS = 10.2) and RBFOX1 (HSS = 11.4)." (PMID 34273561, 2022). "Therefore, what is the relevance of Rbfox1/2 in the pathology of cardiac diseases?" (PMID 28949795, 2018).
brain diseases (1 paper, 2015). "Moreover, 10 genes (ATP1A1, ATP6V1D, C16orf45, CROCC, KLC1, LUC7L2, PIAS2, PRKAR1B, RBFOX1, and RPL19) interacts with at least one brain disease-associated gene." (PMID 26043779, 2015). "As the result, the three genes (ATP1A1 for BD, RBFOX1 for BD, and KLC1 for AD and PD) are directly related to brain diseases." (PMID 26043779, 2015).
RBFOX1 also shares sentences with these, for which no sentence is quoted: attention deficit-hyperactivity disorder (7 papers); neurodegenerative disease (5); Hypertension (3); infection (3); iron deficiency (3); alveolar rhabdomyosarcoma (2); glaucoma (2); hand osteoarthritis (2); periodontitis (2); schizoaffective disorder (2); Adult onset (1); Allergy (1); asthma (1); benign tumors (1); bladder cancer (1); brain tumors (1); Breast Invasive Carcinoma (1); cerebellar ataxia (1); childhood asthma (1); colon adenocarcinoma (1); congenital heart disease (1); diseases of the central nervous system (1); endocrinopathies (1); endometriosis (1); epilepsy syndrome (1); familial dilated cardiomyopathy (1); Fragile X Tremor and Ataxia Syndrome (1); gastric cancer (1); hepatoma (1); Hyperinsulinemia (1).
A further 24 diseases each share a sentence with RBFOX1 in 1 paper.